PALB2 (partner and localizer of BRCA2)
Diseases named in the same sentence as PALB2 in open-access papers (continued):
Sharing a sentence is not in itself a finding about the gene and the disease.
cancer (continued). "Following large‐scale cancer sequence analysis, mutations in other HR‐related genes such as CDK12, ATM and PALB2 were commonly found in mCRPC, and these non‐BRCA DNA repair genes could be used as alternative biomarkers to predict the sensitivity of PARPi." (PMID 36694344, 2023). "In the control group, only one patient had a disease-causing PALB2 variant (0.17%; 1/568) as a secondary finding not related to the disease, which was similar (0.15%; 205/134,187) in the non-cancer control group." (PMID 37686625, 2023). "The patient without a family history of cancer had several germline mutations: a pathogenic PALB2 mutation, and a VUS in ATM, MLH1, CDK4 and BRCA1." (PMID 36359225, 2022). "PV were detected in 13 cancer predisposition genes including ATM (n=4), BLM (n=1), BRCA1 (n=1), BRCA2 (n=7), BRIP1 (n=1), CDKN2A (n=1), CHEK2 (n=9), FANCC (n=1), MUTYH (n=10), NBN (n=1), PALB2 (n=1), RAD51D (n=1) and STK11 (n=1)." (PMID 36091166, 2022). "According to the local testing criteria in use, 73.2% of patients included in this study underwent genetic testing, and 30% of them presented germline likely pathogenic or pathogenic variants in cancer predisposition genes (24 BRCA1, 4 BRCA2, 1 PALB2, 1 NBN, and 1 ATM)." (PMID 36531080, 2022). "Future studies assessing aberrant PALB2 lysine acetylation in cancer tissues and whether KDAC or bromodomain inhibitors, currently in clinical trials for cancer therapy, would modulate PALB2 acetylation may offer therapeutic potential." (PMID 36269050, 2022). "Therefore, an understanding of the functional significance of PALB2 acetylation would have important implications in the context of tumorigenesis, as cancer cells frequently exhibit reprogrammed metabolism and elevated genome instability." (PMID 36269050, 2022). "TIMER 2.0 was used to explore the expression and prognostic role of PALB2 in cancers." (PMID 36158641, 2022). "A recent systematic review identified ATM, BRCA1, BRCA2, CDKN2A, CHEK2, and PALB2 as the most frequent genes harboring GPV in individuals with PDAC not meeting criteria for any cancer predisposition syndrome with varying degrees of family history." (PMID 35805029, 2022). "Thus, we created G > T missense single nucleotide polymorphisms (SNPs) at two different loci in two cell lines: within the 8q24 multi-cancer risk locus in HCT116 cells and within the PALB2 locus in HEK 293 cells." (PMID 35403097, 2022). "Interestingly, the PALB2 expression level was higher in more than 10 types of cancers than that in the normal controls." (PMID 36158641, 2022). "In contrast, carriers of this PALB2 variant are rare in cancer-free FC controls, as none were found in approximately 2000 cancer-free individuals." (PMID 34298626, 2021). "Germline variants in the HR pathway, comprising at least 10 genes, such as BRCA1, BRCA2, ATM, BARD1, BRIP1, CHEK2, NBS1(NBN), PALB2, RAD51C, and RAD51D, lead to inherited susceptibility to specific types of cancers, including those of the breast, ovaries, prostate, and pancreas." (PMID 35008774, 2021). "Given the intimate functional links between PALB2 and BRCA2 and the similar phenotypes associated with biallelic mutations in the genes that encode them, it is plausible that monoallelic PALB2 mutations confer susceptibility to adult cancer." (PMID 33419454, 2021).
cancer (continued). "In addition, as many as 4% of these individuals have germline pathogenic mutations in cancer predisposition genes other than BRCA1 and BRCA2 on MGPT (i.e. CHEK2, PALB2, ATM, NBN, PTEN, etc.)." (PMID 33541411, 2021). "Given the functional interaction of PALB2 with BRCA1 and BRCA2, and the phenotypic similarities of the associated cancers presented within and by others, it is likely these agents will also be of utility in the treatment of PALB2 deficient cancers." (PMID 34113003, 2021). "BRCAness allows for the expansion of the somatic lethality approach to tumors carrying deficiencies in tumor suppressor genes involved in homologous recombination (HR) defective cancers, possessing BRCA1, BRCA2, ATM, ATR, FANC, RAD51, BRIP1, or PALB2 mutations." (PMID 34639169, 2021). "Functional assays may aid in the classification of rare PALB2 VUS, yet a major challenge will be to translate effects on PALB2 protein function into estimates for cancer risk." (PMID 33195396, 2020). "Considering the unambiguous association between RNF168 and PALB2, inhibiting RNF168 signaling in BRCA1-insufficient cancers may be an effective therapeutic strategy." (PMID 32185139, 2020). "Finally, we also highlight the value of this functional analysis in predicting the associated cancer risk and therapy response for VUS in PALB2." (PMID 33195396, 2020). "This study found a 0.2% allele frequency for BRCA1, BRCA2, and PALB2 founder variants in controls with no personal or family history of cancer." (PMID 32300229, 2020). "Although our functional assays may aid in the classification of rare PALB2 VUS, a major challenge will be to translate effects on PALB2 protein function into estimates for cancer risk." (PMID 31757951, 2019). "Heterozygous mutations of BRCA2, BRIP1 (FANCJ) and PALB2 (FANCN) are not sufficient to develop FA phenotypes, but they are associated with a dramatic increased risk for breast, ovarian and other cancers." (PMID 31535215, 2019). "The results of this study suggest a role for the known cancer predisposition gene PALB2 in families with hereditary diffuse gastric cancer and no detected pathogenic CDH1 variants." (PMID 29706558, 2018). "Possible explanations include that nuclear pleomorphism of the cancer cells induces PALB2 expression to promote DNA repair, or PALB2 expression could be induced by cellular proliferation." (PMID 29321957, 2018). "Few reports have evaluated the relationship between PALB2 expression and cancer patient outcomes." (PMID 29321957, 2018). "In the same study, PALB2 was reported to have an incomplete penetrance pattern, typical of moderate cancer risk susceptibility genes, and was estimated that the relative risk for PALB2 truncating variant carriers was 2.3-fold higher than non-carriers." (PMID 28858227, 2017). "PALB2 mutations are considered to be actionable, and are a biomarker for response to Poly (ADP-ribose) polymerase (PARP) inhibitors in pancreatic (ClinicalTrials.gov Identifier: NCT03140670) and prostatic (ClinicalTrials.gov Identifier: NCT02952534) cancers." (PMID 29212173, 2017). "The data support the idea of a transcriptional downregulation of PALB2 in cancer cells, suggesting that PALB2 silencing could be an important mechanism related to tumorigenesis." (PMID 28858227, 2017). "The inhibition of these signalizations could be a mechanism for sensitizing cells to DNA damaging agents, placing PALB2 as a putative target for cancer treatment." (PMID 28858227, 2017).
cancer (continued). "Notably, we observed several novel associations between specific cancer types and genes, including RAD51C in AML, ATM in PRAD, PALB2 and EME2 in STAD." (PMID 26689913, 2015). "A deeper understanding of the function of PALB2 may aid the design of therapeutic strategies for cancer treatment, such as the use of PARP inhibitors." (PMID 23941127, 2013). "Genealogy and genetic studies have reported variability of founder effects in various regions of Quebec, suggesting that demography may also be a factor in the paucity of PALB2 p.Q775X carriers in some studies of French Canadian cancer families." (PMID 23302520, 2013). "One PALB2 p.Q775X positive case was identified among the cancer families not previously investigated for PALB2 mutations." (PMID 23302520, 2013). "Thus, G2/M checkpoint regulators like CtIP, BRCA2 and PALB2 are potential targets for cancer therapy." (PMID 24970150, 2012). "Though any of the detected PALB2 variants do not associate to PRCA in population level in Finland it cannot be ruled out that some of these variants contribute to cancer susceptibility at individual level." (PMID 20003494, 2009). "Subthemes arising under this theme were: general cancer risks and management options (7/19, 36.8%), cancer risks based on family history/ancestry (4/19, 21.1%), insurance (4/19, 21.1%), other genes beyond BRCA1/BRCA2/PALB2 (3/19, 15.8%) and variants of uncertain significance (1/19, 5.3%)." (PMID 40081871, 2025). "Furthermore, BCAC and Cancer Risks Estimates Related to Susceptibility Consortium (CARRIERS), suggested BRCA1, BRCA2, ATM, PALB2, and CHEK2 genes as highly penetrant; both consortiums pinpointed that 10% of BC patients have cancer susceptibility germline mutation." (PMID 38890714, 2024). "Additionally, we assessed the frequency of PALB2 P/LP variants in the gnomAD non-cancer cohort, which showed similar detection ratios in comparison to our cancer control groups (non-HBOC phenotype)." (PMID 37686625, 2023). "Loss of the integral HR pathway components in cancers with non-BRCA HR defects due to germline or somatic mutations in PALB2, RAD51B, RAD51C, or RAD51D, or their inactivation through promoter methylation, might be the cause of olaparib susceptibility." (PMID 35741017, 2022). "While prevalences for ATM, BRCA1, BRCA2, and PALB2 in this study are consistent with prevalences observed in the literature, we calculated that as many as 1.22% of individuals in both cohorts unselected for personal or family history of cancer harbored GPV in CHEK2." (PMID 35805029, 2022). "In addition to PARP inhibitors, cancers with biallelic inactivation of the genes encoding BRCA2 and PALB2 may be particularly sensitive to another alkylating agent, mitomycin C (MMC)." (PMID 36359225, 2022).
cancer (continued). "Although it did not directly conform to Knudson's “two-hit” paradigm, PALB2 may be an example of a cancer predisposition gene." (PMID 33194720, 2020). "Therefore, focusing on moderate-impact or low-impact cancer genes, such as PALB2, might be the way forward for future studies of genes associated with predisposition to disease in these patients." (PMID 29706558, 2018). "However, we noticed that some FA genes such as PALB2 had variants only in HPV+ patients, and we found that patients with at least one variant in a cancer-related FA gene were slightly more likely to be HPV+, although not statistically significant (Fisher’s exact test, OR = 4.19, p = 0.08)." (PMID 30061624, 2018). "Overall, significantly less OC cases are seen in PALB2 families when compared with BRCA1 and BRCA2 families; therefore, it seems that PALB2 may contribute in a different way than BRCA1 and BRCA2 to cancer predisposition, possibly as a result of PALB2 distinct roles in DDR." (PMID 28858227, 2017). "It is known that PALB2 cancer-related missense variants L393W, T1030I and L1143P in the WD40 domain could interfere with PALB2 association with RAD51 and BRCA2, prompting carriers to be defective in DNA damage repair by HR, leading to an increased sensitivity to IR-treatment." (PMID 28858227, 2017). "As PALB2 functions together with BRCA1 and BRCA2, in the same DNA-damage response pathway, it has been thought plausible that PALB2 mutations, similar to BRCA1 and BRCA2 mutations, could predispose to other cancer types." (PMID 27099641, 2016). "Germline mutations in its interacting partner BRCA2 are known to predispose to cancers of the breast, ovary and pancreas, as well as confer a moderate increased risk of CMM (relative risk of 2.6), suggesting by association that PALB2 may also play a role in tumour development in these cancer types." (PMID 24949998, 2014). "Truncating mutations in PALB2 are rare in individuals without cancer." (PMID 23935836, 2013). "Silent and missense sequence variants of the PALB2 gene have been detected in previous studies in both cancer samples and in control tissues, but none of those variants have been strongly associated with cancer susceptibility." (PMID 20122277, 2010). "In this study, the performance and alterations in gene expression of PALB2 and BRIP1,as well as their roles in cancer progression wasinvestigated through conductingquantitative assessments." (PMID 39430039, 2023). "At the same time, in a large-scale study of BC women aged 35–59 years, who were mainly of Northern and Western European descent, PVs in CHEK2, ATM, PALB2, and PMS2 genes were the most frequent among the 25 cancer genes tested, after PVs in BRCA1/2." (PMID 37791908, 2023). "Of these, the most commonly seen are in the Breast Cancer gene 1 (BRCA1), Breast Cancer gene 2 (BRCA2), Checkpoint kinase 2 (CHEK2) and partner and localizer of the BRCA2 gene (PALB2) tumour suppressor genes." (PMID 36831687, 2023). "Interestingly, PALB2 may also affect many immune-related pathways, such as Th17 cell differentiation, the Chemokine signaling pathway, PD-L1 expression, PD-1 checkpoint pathway in cancer, and so on." (PMID 36158641, 2022). "Other highly mutated HR-related genes, including RAD51B (mutation frequency in patients, 6.1%), ATR (6.1%), ATM (6.1%), PALB2 (6.1%), and BRIP1 (4.9%), have been reported to be capable of affecting the sensitivity of various cancer cells to PARPis." (PMID 35952757, 2022).
cancer (continued). "In adult cells, DNA methylation has been extensively demonstrated to be involved in the onset and progression of cancer, mainly through the silencing of tumor suppressor genes such as BRCA1, ATM, and PALB2." (PMID 33808555, 2021). "In this analysis, we only considered genes that were affected in at least four TCGA cases within a cancer type and therefore only seven genes (BRCA1/2, ATM, ATR, PALB2, CHEK2, BRIP1) were included." (PMID 34572800, 2021). "Our patient with the PALB2 alteration had an IDC at 75 years old and reported a family history of cancer, with the mother deceased for BC at 60 years old." (PMID 32365798, 2020). "Thus in these cases, it is possible that the PALB2 variant is not “causative” of the cancer." (PMID 33193564, 2020). "Also, most variants we analyzed showed partially compromised PALB2 function leading to intermediate phenotypes and it is not known at this stage whether or not these defects translate into increased cancer risk and therapeutic response." (PMID 31586400, 2019). "Although the DNA damaging agents have shown clinical efficacy in PALB2-, BRCA1- or BRCA2- cancers, tumor cells often develop resistance to these drugs, with tumor recurrence and progression." (PMID 31877165, 2019). "Cancers in which BRCA2, PALB2, or ATM have been biallelically inactivated are usually susceptible to poly(ADP-ribose) polymerase (PARP) inhibitors or platinum-based agents that facilitates double strand DNA breaks." (PMID 27732944, 2016). "However, prospective data related to the clinical outcomes of PALB2 mutation carriers is lacking and very little information (beyond mutation penetrance) is available to guide current clinical management for carriers (affected and unaffected by cancer)." (PMID 27099641, 2016). "It is worth noting that although LOH in cases with BRCA1 and BRCA2 truncations mutations were largely restricted to OV and BRCA, the majority of LOH truncations in other genes (for example, ATM, PALB2, BAP1, FANCM) were found across cancer types." (PMID 26689913, 2015). "Predicted HFI SNVs were not distributed evenly across disease subsets; SNVs in ULK4, BMP2K, PALB2, ALPK3 were more frequent in triple negative cancers (TNBC) whereas SNVs in EPHA2 was more common in ER positive cancers." (PMID 26420498, 2015). "FANCG, PALB2 and SLX4 homozygous deletions are identified in single carcinomas while FANCM homozygous deletions are identified in 2 carcinomas." (PMID 26438152, 2015). "Carcinomas with homozygous deletions in either MRE11A, RAD50, ATRIP or PALB2, 4 genes that are essential for mammalian cell viability, are present in the publically available TCGA database." (PMID 26438152, 2015). "Therefore, this study aims to describe the age of onset and clinicopathological characteristics of BC and OC patients with a PALB2, RAD51C, or RAD51D GPV and compare these characteristics to national cancer registry data." (PMID 40428378, 2025). "Expression of innate immune system markers (APOBEC3A/B), DNA repair genes (BRCA1, BRCA2, PALB2, RAD51), cell cycle genes (CCNA2 and CCNE1), a cell proliferation gene (MELTF), and a T-cell regulator (Treg) marker (FOXP3) was elevated in cancer compared to precancer and controls." (PMID 39672307, 2024). "Among the two control groups (cancer patients with non-HBOC tumors and healthy control, non-cancer population), we found that the PALB2 P/LP detection rate was low (0.088% and 0.076%, respectively)." (PMID 37686625, 2023). "Previous research has shown that many human cancers exhibit BRCA-like mutational signature without harboring any BRCA1, BRCA2, or PALB2 mutations." (PMID 37032811, 2023). "Expectedly, HBOC patients had a higher risk of detecting PALB2 P/LP variants compared to non-HBOC patients and the non-cancer population with OR 8.1 and 9.3, respectively." (PMID 37686625, 2023).